MMP9 (matrix metallopeptidase 9)
Diseases named in the same sentence as MMP9 in open-access papers (continued):
Sharing a sentence is not in itself a finding about the gene and the disease.
tumor (continued). "MMP-9 promotes tumor angiogenesis and accelerates hematogenous metastasis by degrading type IV collagen in tumor tissue and promoting VEGF release, thereby inducing metastasis and invasion of ESCC." (PMID 37359527, 2023). "Accordingly, there has been an increased production of extracellular matrix proteins such as fibronectin 1 (FN1), MMP1, and MMP9 in chronic inflammatory and tumor states of the cervix." (PMID 36831674, 2023). "IL-1β treatment significantly increased MMP9 expression in mouse tumor tissues on the basis of the results of qPCR (9.57 ± 0.26 vs. 1.08 ± 0.44, P < 0.0001) and western blotting (1.13 ± 0.07 vs. 0.21 ± 0.04, P < 0.0001)." (PMID 37106440, 2023). "The CCND family is involved in the regulation of tumor cell proliferation, and MMP9 can degrade components of the extracellular matrix and plays a significant role in pathophysiological functions." (PMID 37263638, 2023). "Multivariate logistic regression found tumor diameter, positive nodal status at diagnosis and matrix metalloproteinase-9 (MMP-9) mRNA expression in the residual tumor to be factors associated with the absence of response to NAC." (PMID 37511057, 2023). "Tumor‐associated marker expression was significantly different among all cell types for MMP2, MMP7, MMP9, MMP12, ABHD5, ADAMTS1, AP‐1, and MGLL each with p < 0.001." (PMID 38037545, 2023). "There is also a documented relationship between Sp1 and the upregulation of MMP9, a previously highlighted gene involved with tumor invasion and metastasis." (PMID 37373974, 2023). "MMP9, as one of the crucial proteins, can participate in tumor development processes such as tumor angiogenesis and immune evasion through hydrolysis of adhesion molecules." (PMID 37200633, 2023). "Among these genes, FCGR2A, FYN, ITGB2, and VSIG4 protein levels were increased in tumor tissues, while MMP9 protein level was decreased, which was consistent with their mRNA expression levels." (PMID 38022584, 2023). "Tumor cells‐secreted CXCL1 and CXCL8 recruit neutrophils and promote activation of ERK and JNK signaling pathways and expression of VEGFA and MMP9 in neutrophils, which induce tumor lymphangiogenesis and facilitate LN metastasis of tumor cells." (PMID 36670069, 2023). "Further examination on preoperative GBM samples found a distinct difference between the original tumour and the recurrence based on MMP-9 levels of serum sEVs, and the recurrence showed a lower level of MMP-9 on average (p < 0.0001)." (PMID 36765669, 2023). "Three target MMP enzymes were selected for the MMP inhibition assay, the collagenase MMP-1, and the gelatinases MMP-2 and MMP-9, which are upregulated in a number of tumor types." (PMID 37108137, 2023). "We focused on the expression of matrix metalloproteases (MMPs), particularly MMP-9, a key protein in tumor progression that facilitates migration and invasion, thereby promoting tumor metastasis." (PMID 36674806, 2023). "MMP-2 and MMP-9 are often considered targets for antitumor therapy due to their crucial roles in degrading the extracellular matrix and promoting tumor invasion and metastasis." (PMID 38003553, 2023). "Jiguet-Jiglaire and colleagues recently demonstrated that MMP-9 is expressed by tumor-infiltrating neutrophils in GB tissue." (PMID 37190125, 2023). "It is worth mentioning that research has shown MMP-9's ability to regulate tumor immune surveillance by modulating the expression of PD-L1." (PMID 38087364, 2023). "Our recent report demonstrated that CXCL10, the increased inflammatory cytokine resulted from liver graft injury, recruited MDSCs into liver graft through TLR4/MMP9 to promote tumor recurrence post transplantation." (PMID 37175922, 2023). "Specifically, our protein expression data showed both a trend of increased MMP2 levels and a significant increase in MMP9 levels in lungs from mice growing orthotopic MDA-MB-231-tdTomato tumor xenografts compared to lungs from normal mice as controls." (PMID 37903851, 2023).
tumor (continued). "Matrix metalloproteinase (MMP)-2 and MMP-9 degrade the extracellular matrix and basement membrane and play key roles in tumor invasion and metastasis." (PMID 37006921, 2023). "As a result of neutrophils' presence in the lungs, pro-metastatic molecules such as S100A8, S100A9, Bv8, and MMP9 are elevated, supporting tumor cell growth in the lungs." (PMID 37158964, 2023). "The statistical analysis did not confirm the presence of the correlation between the expression of TIMP1 (p = 0.4306), MMP2 (p = 0.9208) or MMP9 (p = 0.8674) in blood before surgical removal of tumor tissue and survival of patients with NSCLC." (PMID 37509417, 2023). "Cytokines preferentially secreted in M0 and M2 co-culture platforms were IL8 and MMP-9 which is consistent with the known role of these cytokines in promoting angiogenesis and tumor invasion." (PMID 37835577, 2023). "Tumor cells, pro-neoplastic neutrophils and even tumor-derived fibroblasts secrete MMP-9 to mediate the degradation of the tissue basement membrane type IV collagen to promote tumor growth and stimulate VEGF to promote vascularization." (PMID 37063873, 2023). "In this line, several authors have found elevated levels of MMP-9 in LC brain metastases compared to other tumors, suggesting a crucial role in the migration of tumor cells from the tumor circulation into the CNS through the blood-brain barrier." (PMID 38283359, 2023). "MMP-9 inhibitors promote the normalization of hematopoietic function, thus reducing the production of MDSCs in tumor-bearing BALB-neuT mice expressing an activated rat c-erbB-2/neu transgene model." (PMID 37006306, 2023). "HIF activation in the hypoxic TME also induces the expression of a number of genes, such as VEGF or matrix metalloprotease 9 (MMP9), that affect macrophage polarization and drive tumor progression." (PMID 36816959, 2023). "The genes positively associated with NLR (CD39 (ENTPD1), PTEN, MYD88, MMP9 and LDH) are involved in processes of immunosuppression, inflammation and tumor-promoting activity." (PMID 37684649, 2023). "Similar results were obtained for the second of the gelatinases, where the tumor tissue was also characterized by the expression of MMP9 above the normal level." (PMID 37509417, 2023). "In this study, we developed a novel strategy that targeted both MMP-9 and fibronectin in the tumor microenvironment (TME)." (PMID 36978072, 2023). "LncRNA LINC0031 reduces the expression of MMP-9, suppresses the activation of the P13K/Akt signaling pathway, and inhibits tumor progression." (PMID 37175113, 2023). "Matrix metalloproteinase-9 (MMP9) was upregulated by macrophages in response to TNFα and interleukin 1β enriched in the tumor microenvironment DM secondary to PDAC." (PMID 36769405, 2023). "The study has shown that MMP9 promotes tumor progression by regulating tumor immune infiltration in ccRCC30." (PMID 37117633, 2023). "TMPRSS2-ERG fusions are responsible for checkpoint impairment in the cell cycle and for tumor proliferation, but also tumor cell migration and invasiveness by overexpression on metalloproteinase 9 (MMP9) and plexin A2." (PMID 37021836, 2023). "The angiogenic process begins with the recruitment of blood vessels in response to the release of growth factors and cytokines by tumour cells and the secretion of proteases such as MMP-9." (PMID 38203696, 2023). "In a variety of malignant tumors, MMP-2 and MMP-9 overexpression generally leads to increased tumor angiogenesis, invasion, and metastasis." (PMID 36980704, 2023). "Specifically, MMP9, MMP13, MMP11, and CEMIP were positively associated with the tumor immune microenvironment, while SLPI, SLC2A1, SERPINB5, HK2, CEACAM6, and CEACAM5 were negatively associated with the tumor immune microenvironment." (PMID 37234801, 2023). "We also found that patients with larger tumor size (> 4 cm) had significantly higher expression of MMP-9 and CCR7 (P<0.002 and P<0.001, respectively)." (PMID 37600570, 2023).
tumor (continued). "In spite of that, Ginsenoside Rh2 was also proven to transform the macrophage phenotype from M1 to M2, thereby decreasing VEGF, MMP-2, and MMP-9 expression, eventually inhibit the spread and enlargement of tumours." (PMID 37742025, 2023). "Primary tumor-derived VEGF specifically upregulates matrix metalloproteinase 9 (MMP9) in pre-metastatic lung ECs via VEGFR-1/Flt-1 tyrosine kinase and thereby promotes lung metastasis by enhancing tumor cell invasion." (PMID 37222464, 2023). "The role of MMP-2 and MMP-9 in the degradation of ECM significantly contributes to tumor invasion and the aggressiveness of GBs, while the aberrant expression of VEGFA is suggested to drive angiogenesis and tumorigenesis." (PMID 37190125, 2023). "In a nude mouse xenograft model, MMP9 knockdown inhibited tumor growth, reduced tumor volume, and prolonged survival time." (PMID 36677584, 2023). "Snail is reported to be a key tumor progression and metastasis regulator via increasing MMP9 expression and tumor invasion." (PMID 37239383, 2023). "It is interesting to note that the expression of MMP-9 was positively correlated with tumor recurrence (r = 0.23, p = 0.03), and patients with MMP-9 positivity had a 2.63-fold increased risk for relapse (B = 0.97, p = 0.03)." (PMID 36831707, 2023). "Macrophages express CCR2 were recruited by CCL2 that result in up regulating their expression levels of angiogenic factors, such as IL− 6, VEGF, and MMP9, which contributed to tumor vascularization." (PMID 36816959, 2023). "Survival analysis showed that patients with positive MMP-9 expression had worse PFS and a higher risk of tumor recurrence." (PMID 36831707, 2023). "This protein not only degrades extracellular matrix protein but also acts as an activator of other MMP zymogen including MMP2 and MMP9, playing a key role in tumor invasion." (PMID 37229458, 2023). "Mast cells release VEGF-A, VEGF-C, VEGF-F, CXCL-8, MMP-9, and other factors, which promote tumor angiogenesis." (PMID 37161430, 2023). "4T1 orthotopic tumor sections were rich in MMP-9 and fibronectin expression, and after treatment with CREKA-GK8-QC, strong Cy5.5 fluorescence was observed." (PMID 36978072, 2023). "As a result of ECM and basement membrane degradation, it is believed that MMP9 is involved in tumor migration, invasion, metastasis, and angiogenesis." (PMID 37373974, 2023). "C-myc has been recognized as a proto-oncogene that can be malignant by uncontrolled cell proliferation due to its overexpression, and the degradation of extracellular matrix by MMP-9 plays a critical role in tumor invasion and metastasis." (PMID 37460940, 2023). "MMP-9 is an important target for tumor therapy via inhibiting amplification of MDSCs and facilitating formation of the TME." (PMID 37006306, 2023). "Treatment with EJ inhibits STAT3, which reduces the expression and secretion of the MMP-2 and MMP-9 proteins and exerted an anti-tumor metastasis effect." (PMID 37049904, 2023). "Matrix metalloprotein-2 (MMP-2) and Matrix metalloprotein-9 (MMP-9) are markers of tumor invasion and metastasis." (PMID 37187758, 2023). "NF-κB can also contribute to tumor invasion by induction of matrix metalloproteinase 9 (MMP9) that degrades the extracellular matrix and provides a suitable niche for the invasion of cancerous cells." (PMID 36687217, 2023). "The ECM-degrading enzyme metalloproteinase 9 (MMP9) plays an important role in promoting the invasion of tumor cells into other tissues; thus, it directly contributes to carcinogenesis." (PMID 37834295, 2023). "Cathepsin G is implicated in MMP-9 activation, compromises cell adhesion via E-cadherins and enhances TGF-β signaling, thus promoting tumor cell migration." (PMID 38139365, 2023). "Next, we evaluated the effect of HNGF6A on the secretion of active metalloproteases (MMP) MMP-2 and MMP-9, which are essential for tumor cell invasion, by means of zymography in media from GBM U251-MG cells treated with HNGF6A." (PMID 37627089, 2023).
tumor (continued). "There was no expression of molecular indicators representing malignant behaviours, e.g., PCNA, CD44v6, and MMP-9 in HIFU-treated tumours compared to the control group." (PMID 37568958, 2023). "First, the enzymatic breakdown of the peptide sequence, GALGLPG (GG), in the TME by MMP-2 and MMP-9 overexpression permits tumor-specific accumulation and retention of BLPNs." (PMID 37144580, 2023). "We investigated how SMPDL3B affects various key EMT proteins (E-cadherin, ZO-1, vimentin, and MMP-9) because epithelial-mesenchymal transformation (EMT) is a significant route of tumor cell migration and invasion." (PMID 38813495, 2023). "Among neutrophil-released proteases, matrix metalloproteinases (MMPs) play a significant role in the development of tumor angiogenesis, particularly MMP-9." (PMID 37158964, 2023). "Through PPI and CT network analysis, 17 important targets were identified, and 2 pivotal target genes, MMP2 and MMP9, were validated as upregulated in GC and involved in the tumor immune microenvironment." (PMID 37565919, 2023). "Luteolin further determines the suppression of matrix metalloproteinase-2 (MMP-2) and MMP-9, thus inhibiting angiogenesis an invasion, two key mechanisms of tumor progression and metastasis." (PMID 38203299, 2023). "TAMs are also involved in the secretion of various pro-angiogenic factors, such as vascular endothelial growth factor (VEGF), fibroblast growth factor (FGF), and matrix metallopeptidase 9 (MMP-9), associated with tumor angiogenesis." (PMID 37894474, 2023). "MMP-2 and MMP-9, in particular, aid in the digestion of plasminogen and the release of angiostatin, which increases tumor cell apoptosis, and MMP-9 also breaks down collagen XVIII to produce endostatin, which inhibits angiogenesis." (PMID 37823051, 2023). "The luciferase promoter construct was efficiently transfected into tumor cells to investigate MMP-9 promoter activity." (PMID 36674806, 2023). "MMP9 mediates tumor invasion, metastasis, and immune escape through a pro-oncogenic signaling pathway and is associated with relapse and poor prognosis in patients with CRC." (PMID 37106440, 2023). "CCL2 and CCL3 influence monocyte recruitment and production of MMP9, thus promoting tumor invasion and metastasis." (PMID 37947617, 2023). "In particular, MMP14 can control the formation of invasive pseudopodia, while MMP2 and MMP9 play a key role in tumor invasion." (PMID 37686118, 2023). "M2 macrophages secrete EGF, matrix metalloprotein 9 (MMP-9), and other proteins to suppress antitumor effects and promote tumor progression." (PMID 36843929, 2023). "MMP9 plays a core role in the degradation of the extracellular matrix and basement membrane of cancers to contribute to tumour invasion and metastasis." (PMID 37753805, 2023). "Subsequently, the expression of other markers, CD31 and MMP9, was used to demonstrate the degree of tumor angiogenesis and metastasis, respectively." (PMID 37375842, 2023). "Nanoparticle-mediated delivery enabled tumor-specific targeting and inhibited TAK1 phosphorylation and MMP9 expression in tumor tissues, suppressing primary tumor growth and lung metastasis in vivo." (PMID 37041137, 2023). "The most representative and most substantial evidence comes from MMP-9 detection in tumor tissues, and the serum levels only partly reflect the tumor situation." (PMID 37175113, 2023). "Several proteins are involved in this process, such as MMP-9, which plays an important role in promoting tumor growth." (PMID 37175359, 2023). "In turn, neutrophilia promotes the secretion of vascular endothelial growth factor (VEGF), matrix metalloproteinase 9 (MMP-9), which in turn accelerates tumor development." (PMID 36855112, 2023). "Other TME-associated cells, such as T-regulated cells, dendritic cells, and tumor-associated adipose cells, also secrete pro-angiogenic factors, such as VEGFA, MMP9, IL10, TGF-β, and leptin, and consequently promote cancer angiogenesis." (PMID 36647777, 2023).
tumor (continued). "While both macrophages and IBC cells can promote TIME sprouting independently, the combination of macrophages and IBC cells demonstrates enhanced secretion of IL8 and MMP9, which are known to promote angiogenesis and tumor invasion." (PMID 37835577, 2023). "Reactive astrocytes close to extravasating metastatic tumor cells in the brain, also overexpress and release MMP9 favoring the development of brain metastasis." (PMID 38293652, 2023). "Previous studies have reported that LCN2 and MMP9 form a heterodimer through disulfide bonding to protect MMP9 enzyme activity, contributing greatly to tumour invasion and metastasis." (PMID 37753805, 2023). "MMP2 and MMP9 are two matrix metalloproteinases that play a critical role in tumor cell invasion and metastasis." (PMID 37270527, 2023). "Matrix metalloproteinase 9 (MMP9) is a 92 kDa gelatinase that plays important roles in tumor invasion and angiogenesis." (PMID 36756017, 2023). "On the other hand, we identified repressed genes such as Mdk, Fap, Mmp9, Itga6, and Cxcl12, known as mediators of tumor growth, migration, invasion, and fibrosis." (PMID 36765032, 2023). "This induction occurs in the BMSCs, while at the same time, tumor cells appear to attenuate their MMP-9 promoter activity." (PMID 36674806, 2023). "SCC can produce a large amount of MMP9 via stimulation by collagen I, thus establishing bone metastasis and releasing tumor cell chemokines during osteolysis." (PMID 37377915, 2023). "The overexpression of Rab1B and MMP-9 in CRC tissues was associated with metastasis, advanced tumor stage, and poor OS." (PMID 37446127, 2023). "TANs sustain tumor angiogenesis through the release of the pro-angiogenic factors MMP9, BV8, and S100 proteins S100A8/9." (PMID 36647777, 2023). "The secretion of substances like transforming growth factor-beta and the vascular endothelial growth factor is stimulated by MMP-9, which promotes angiogenesis and tumor growth." (PMID 36938194, 2023). "The PPI network indicated that SSA1 was co-expressed with MMP1, MMP3, and MMP9; together, they played an important role in tumor invasion and metastasis." (PMID 37081987, 2023). "To further validate, we performed Immunofluorescence (IF) staining for MMP9 and CTSK in the tumor patient tissues and found that both MMP9 and CTSK had a co-localization with CD68." (PMID 38123589, 2023). "Potential downstream effectors in the signaling pathways involved in AQP1-mediated tumor progression include β-linked protein, Lin-7, FAK, MMP2, MMP9, and histone proteinase B." (PMID 37334171, 2023). "MMP-2 and MMP-9 are involved in the remodeling process of the extracellular matrix, increasing its secretion during invasion and tumor metastasis." (PMID 38137922, 2023). "The main figure of the network of regulator effects showed “migration of cells,” “invasive tumor,” “proliferation of cells,” “advanced malignant cancer,” and “apoptosis” through the suppression of genes such as MMP9 and FN1." (PMID 36996146, 2023). "In recent decades, several studies reported the upregulation of MMP-9 in the source of tumour tissue, which provides the opportunity to identify MMP-9 in the serum as well." (PMID 36765669, 2023). "This dual-ratiometric imaging probe quantitatively revealed that the overexpression of MMP-9 at tumor sites and the spatial heterogeneity of abnormal microenvironmental pH and synergistically guide in vivo tumor invasion in a mouse model of colon cancer." (PMID 35154500, 2022). "BB94 is a potent extracellular broad-spectrum MMP inhibitor that inhibits MMP-1, MMP-2, MMP-3, MMP-7, and MMP-9 and distant tumor metastases." (PMID 35440570, 2022). "Many molecular pathways of TNF-alpha are associated with the upregulation of matrix metallopeptidase 9 [MMP9] which directly degrades the extracellular matrix allowing tumor migration and indirectly promotes cytokines that support cell tumor growth." (PMID 36672607, 2022).